ZNF331 (zinc finger protein 331)
Diseases named in the same sentence as ZNF331 in open-access papers (continued):
Sharing a sentence is not in itself a finding about the gene and the disease.
tumor (continued). "Given the role of ZNF331 as a putative tumor suppressor and the findings demonstrating the important tumor-suppressing functions of zinc-finger proteins and their promising application in cancer therapy, it is worth exploring the functional role of this gene in CLL." (PMID 26355846, 2015). "By categorizing tumor-specific CNA regions in metastases, we found that alterations of oncogenes and tumor suppressors, for instance, tumor suppressor PMS2 and oncogenes TFPT, ZNF331, and others, may be linked to metastatic progression." (PMID 24405831, 2014). "Bioinformatics analysis revealed that APOC1, CFH, LGALS1 and NUSAP1 were highly expressed in bone metastases compared to primary tumours, whereas ADRB2, NR4A2 and ZNF331 exhibited the opposite trend (p < 0.05)." (PMID 39098992, 2024). "For example, ZNF545, ZNF569, ZNF383, and ZNF331 are reported to act as tumor suppressor genes, while ZNF147, ZNF217, ZNF278, GLI1, and Evi9 promote tumor progression." (PMID 33566221, 2021). "Recently, several novel putative tumour suppressors such as BCL6B 16, CPEB1 17, ZNF331 18, ZNF545 19 and CHIP 20 have been identified in GC." (PMID 30714150, 2019). "When taking into account the different tumour subtypes, we detected 24 SNPs (in eight genes: ZDBF2, PEG10, MEST, H19, IGF2, MEG3, ZNF331 and HM13) exhibiting DI in at least one subtype compared to the normal tissue samples." (PMID 30297886, 2018). "According to Cox proportional hazards model analysis, ZNF331 methylation was an independent prognostic factor for poor 5-year OS and 5-year DFS after adjusting for tumor differentiation and TNM stage (both p < 0.05)." (PMID 29075358, 2017). "In contrast, CD8 effector cells exhibited downregulation of multiple key genes involved in tumor-suppressive transcriptional regulation (HIST1H1C, ZNF331, KLF6, and BTG1) and immune activation and trafficking (CXCR4, CD69, and TNFAIP3) in LS carriers, which was more severe in LS-CRC." (PMID 40909768, 2025).
cancer (17 papers, 2010 to 2025). A tumor composed of atypical neoplastic, often pleomorphic cells that invade other tissues. "Limited preclinical data suggest that loss of ZNF331 expression reduces cancer cell proliferation in vitro and in vivo and enhances invasive capacity in vitro." (PMID 38716804, 2024). "ZNF331, a zinc-finger transcription factor, has been found often hypermethylated (a status linked to increased expression) within peripheral blood leukocytes in various cancers." (PMID 39940906, 2025). "While not statistically significant, there was a numerical reduction in OS and DFS in patients with cancers that demonstrated ZNF331 methylation who received IFL compared to those who received FU/LV." (PMID 38716804, 2024). "Studies have shown that the promoter region of ZNF331 is frequently methylated and serve as a poor prognostic marker for several types of cancers." (PMID 37165378, 2023). "The possibility that ZNF331 is ubiquitously imprinted argues for further study of its function in metabolism, behaviour, fetal development and cancer." (PMID 20403199, 2010). "Also, for other genes featuring a combination of downregulation and LOI in cancer, e.g., for ZDBF2 and ZNF331, also observed in cancer cells in this study, incorrect transcript usage should be further explored." (PMID 39766305, 2024). "Our results showed that ZNF331 was involved in the transition of both LA-TAMs and pDCs, which exhibited a dysregulated immune phenotype, suggesting it may regulate the anti-cancer function of myeloid cells." (PMID 37649596, 2023). "Similarly, we identified 57 potential TSGs, of which at least 13 have been implicated in cancer, including HOXB13, ZNF350, ZNF331, CNTNAP2, NEFH, and ABR with reduced expression due to hypermethylation or loss." (PMID 37245006, 2023). "In our study, we have compared top DASE loci identified in our genome-wide ASE studies with the current cancer genome database provided by Cancer Gene Census (Sanger Institute) and have identified two DASE loci (USP6 and ZNF331) listed as cancerous genes." (PMID 23107584, 2012). "The most frequently epimutated regions varied depending on tissue origin, with the maternally methylated ZNF597 DMR being affected in 66.6% of hepatocarcinoma cell lines, H19 in 28.9 % of lung, ZNF331 DMR1 in 32% of colon and GRB10 in 44.9% of breast-derived cancer cell lines." (PMID 28883545, 2017).
ZNF331 also shares sentences with these, for which no sentence is quoted: Thyroid adenoma (2 papers); asthma (1); esophageal cancer (1); head and neck cancer (1); kidney cancer (1); leukemia (1); liver cancer (1); oesophageal cancer (1); ovarian carcinoma (1); Parkinson's (1).